IL6 (interleukin 6)
Diseases named in the same sentence as IL6 in open-access papers (continued):
Sharing a sentence is not in itself a finding about the gene and the disease.
atherosclerosis (continued). "We found that FC peel extract down-regulates IL-6 in both monocytes and endothelial cells, suppresses endothelial activation and monocyte-endothelial cell adhesion, thus alleviates atherosclerosis." (PMID 41515139, 2025). "Intracellular ROS can activate NF-κB, which regulates genes involved in atherosclerosis and inflammation, including interleukin-6 (IL-6)." (PMID 41189994, 2025). "The role of IL-6 in accelerated atherosclerosis in athletes, therefore, warrants further investigation." (PMID 39957063, 2025). "Currently, drugs inhibiting the pro-inflammatory interleukin-6 (IL-6), such as Ziltivekimab and Clazakizumab, are undergoing clinical trials for atherosclerosis therapy (see review)." (PMID 41226613, 2025). "In atherosclerosis, IL-6 promotes vascular inflammation by encouraging smooth muscle cell proliferation, endothelial dysfunction, and the activation of inflammatory mediators." (PMID 40244022, 2025). "M1 macrophages release pro-inflammatory factors like TNF-α, IL-6, and IL-1β, contributing to foam cell formation and accelerating atherosclerosis plaque development." (PMID 40276600, 2025). "Research on the progression of atherosclerosis has indicated that ascending levels of inflammatory factors such as CRP and interleukin 6 play a role in chronic inflammation during the process of atherosclerosis formation." (PMID 39949401, 2025). "Pro-inflammatory cytokines, such as IL-1β, IL-6, TNF-α, and IFN-γ, are crucial in the inflammation associated with atherosclerosis." (PMID 39941424, 2025). "Simultaneously, inflammatory markers like C-reactive protein and interleukin-6 accelerate atherosclerosis by increasing endothelial dysfunction, lipid deposition, and vascular calcification." (PMID 40011291, 2025). "An important player in the pathophysiology of atherosclerosis, interleukin 6 (IL-6) is a multifunctional proinflammatory cytokine with wide-ranging biological effects." (PMID 40218291, 2025). "Studies have shown that mutated myeloid cells derived from CHIP clones exhibit a pro-inflammatory phenotype, with enhanced production of interleukin-1β (IL-1β) and interleukin-6 (IL-6), key mediators in the pathogenesis of atherosclerosis and vascular injury." (PMID 41458386, 2025). "Secondly, TCAs suppress cytokine production, including pro-inflammatory cytokines such as TNF-α, IL-1β, and IL-6, which are key mediators in the pathogenesis of atherosclerosis." (PMID 40006011, 2025). "One of the areas where the anti-inflammatory effects of TCAs are particularly intriguing, yet controversial, is their influence on the IL-6 pathway and its implications for atherosclerosis." (PMID 40006011, 2025). "Atherosclerosis (AS) is a chronic inflammatory disease where the release of pro-inflammatory cytokines (e.g. IL1β, IL6, and TNF) promotes its development." (PMID 39044161, 2024). "The effect of IL-6 is relevant due to its contribution to atherosclerosis and vulnerable vascular lesions." (PMID 39372701, 2024). "The results of our study showed that PMA, PNA, and IL‐6 are key elements in the pathogenesis of atherosclerosis as well as ACS and that these parameters can have diagnostic value." (PMID 39669190, 2024). "IL-6 plays a direct role in activating endothelial monocytes and macrophages, thereby accelerating plaque accumulation and atherosclerosis." (PMID 39077632, 2024). "It has been reported that IL-6 is a crucial factor in the early onset of atherosclerosis and has been proposed as a marker indicating a broader extent of atherosclerotic lesions." (PMID 37838929, 2024). "IL-6 not only reflects inflammatory status but also contributes to the progression of atherosclerosis by promoting endothelial dysfunction and plaque instability." (PMID 39057626, 2024).
atherosclerosis (continued). "This latter condition is associated with systemic inflammation and a surge in pro-inflammatory cytokines such as tumor necrosis factor-alpha (TNF-α) and interleukin-6 (IL-6), which are pivotal in atherosclerosis and CVD pathogenesis." (PMID 38540305, 2024). "MMP9 correlated with left ventricular dysfunction after myocardial infarction, atherosclerosis coronary artery disease, and is increased by proinflammatory cytokines, such as interleukin-1 (IL-1), IL-6 and tumor necrosis factor α (TNFα)." (PMID 39273682, 2024). "The JAK-STAT pathway also plays a crucial role in atherosclerosis through its action on IL-6 and TNF." (PMID 38929699, 2024). "The expression levels of miR-146a correlate with the expression levels of IL-6 and TNFα in patients with atherosclerosis." (PMID 38927529, 2024). "The association of ENST00000416361 with inflammatory cytokines (IL-6 and TNF-α) and lipid metabolism-related genes (SREBP1 and SREBP2) suggests its involvement in atherosclerosis pathogenesis through inflammation and lipid metabolism." (PMID 39273193, 2024). "Vascular smooth muscle cells are known to be a source of IL-6, which has been shown to play an important role in atherosclerosis." (PMID 38256155, 2024). "For example, macrophages secrete vimentin during atherosclerosis, which stimulates pro-inflammatory cytokines such as interleukin-6 (IL-6) and tumor necrosis factor-α (TNF-α)." (PMID 39057066, 2024). "It downregulates E-selectin expression and decreases NLPR3 inflammasome activation, suppressing IL-1β and IL-6 release, which are critical inflammatory mechanisms in atherosclerosis." (PMID 39113913, 2024). "The level of IL-6 shows a positive correlation with BMI and participates in the regulation of lipid metabolism, which is the basis of the pathogenesis of atherosclerosis." (PMID 39200092, 2024). "In individuals with subclinical atherosclerosis, a positive correlation between IL-6 levels and CIMT was identified." (PMID 37838929, 2024). "IL-6, as one of the most important pro-inflammatory cytokines, is closely related to cardiovascular diseases such as atherosclerosis, hypertension, cardiomyopathy, and cardiac fibrosis." (PMID 38878214, 2024). "IL-6 and IL-1β influence various stages of atherosclerosis, from the early recruitment of leukocytes to the development of advanced atherosclerotic lesions." (PMID 39057626, 2024). "Beyond that, increased inflammatory mediators, such as NF-κB, IL-6, and TNF-α (related to ROS and inflammation excess), increase the risk of atherosclerosis injuries and damage in the liver vessels." (PMID 39458995, 2024). "M1 macrophages primarily drive inflammatory responses and disease progression in atherosclerosis through the secretion of pro-inflammatory cytokines (such as IL-1β, IL-6, and TNF-α) and the generation of reactive oxygen species (ROS)." (PMID 39726810, 2024). "Potential targets such as GAPDH, AKT1, TNF, IL6, and SRC were implicated in key pathways including MAPK signaling pathway, lipid and atherosclerosis, PI3K-Akt signaling pathway, and IL-17 signaling pathway." (PMID 39822742, 2024). "In patients with type 2 diabetes and macrovascular atherosclerosis, higher circulating IL-6 levels are observed compared to those with atherosclerosis alone." (PMID 39766337, 2024). "As flaxseed oil displayed anti-atherosclerosis action against high-fat diet-induced ApoE−/− mice, Intestinimonas was positively correlated with LPS and IL-1β in plasma and with IL-6 and IL-1β in the aorta." (PMID 39403395, 2024). "These pathways can promote the release of inflammatory cytokines, such as tumor necrosis factor-alpha (TNF-α) and interleukin-6 (IL-6), which have been shown to contribute to endothelial dysfunction and atherosclerosis." (PMID 39057624, 2024). "IL-6 is believed to be involved in promoting the occurrence and progression of atherosclerosis through multiple pathways." (PMID 39065817, 2024).
atherosclerosis (continued). "Recent studies have shown the important role of IL-6 in the development of atherosclerosis, as well as many immune-mediated diseases, including periodontitis." (PMID 38396821, 2024). "IL-6 and CRP are widely studied inflammatory markers and have been found to be associated with atherosclerosis plaque development, especially in elderly stroke and transient cerebral ischemia patients." (PMID 37611898, 2024). "Elevated levels of inflammation-related proteins, including fibrinogen, high-sensitivity C-reactive protein (hsCRP), and interleukin-6 (IL-6), are observed in individuals with atherosclerosis." (PMID 38622622, 2024). "It is well established that the proinflammatory cytokine IL-6 plays an important role in the development of atherosclerosis." (PMID 39654623, 2024). "For example, one study associated H. pylori infection with elevated inflammatory markers like C-reactive protein (CRP) and interleukin-6 (IL-6), which contribute to endothelial dysfunction and atherosclerosis progression." (PMID 39202269, 2024). "This response alleviates inflammation by reducing pro-inflammatory markers such as TNF-α and IL-6, which play a role in the progression of atherosclerosis." (PMID 39728298, 2024). "Inflammatory cytokines, such as tumor necrosis factor alpha (TNF-α), interleukin 1 beta (IL-1β), and interleukin 6 (IL-6), are pivotal in the inflammatory response that characterizes atherosclerosis." (PMID 38831182, 2024). "Fatty acid binding protein 4 upregulates macrophage inflammation-related interleukin-6 (IL-6) level and regulates lipid metabolism in atherosclerosis induced by activation of the JAK2/STAT2 pathway." (PMID 38835896, 2024). "The heightened IL‐6 expression is strongly related to developing a wide range of cardiovascular disorders, including atherosclerosis, myocardial infarction, heart disease and ischemic stroke." (PMID 39160453, 2024). "A notable increase in serum IL‐1β, IL‐18, and IL‐6 levels was observed in atherosclerosis mice, and METTL3 knockdown in atherosclerosis mice significantly decreased these inflammatory markers." (PMID 39432244, 2024). "Numerous studies have examined the role of IL-6 in the pathophysiology of atherosclerosis particularly examining the relationship between the inflammatory process and peripheral artery disease (PAD)." (PMID 38961103, 2024). "Evidence suggests that adipokines such as adiponectin, leptin, and interleukin-6 can play important roles in atherosclerosis development, progression, as well as regression." (PMID 39684379, 2024). "Elevated concentrations of HMGB-1 and IL-6 have also been correlated with the occurrence of CVDs, including myocardial infarction and atherosclerosis." (PMID 39876967, 2024). "Clinical and experimental studies implicate IL-6 in the progression of cancers and CVDs, including hypertension, atherosclerosis, aortic and thoracic aneurysms, cardiac fibrosis, aortic dissection, cardiomyopathy, heart failure, and ischemic stroke." (PMID 38570838, 2024). "TMAO is also associated with disease processes in murine models of atherosclerosis, where it is tied to foam cell formation, NLRP3 inflammasome activation, and generation of the proinflammatory cytokines IL-1β, TNF-α, and IL-6." (PMID 37720032, 2023). "In fact, the roles of TNF-α and IL-6 in VSMCs have been the subject of extensive research due to their significant implications for cardiovascular diseases such as atherosclerosis, restenosis, and hypertension." (PMID 37873791, 2023). "High levels of these cytokines are associated with lower survival in dialysis and studies indicate that inflammation correlates strongly with atherosclerosis, with IL-6 being a good predictor of the inflammatory burden in this group of patients." (PMID 37755957, 2023). "The JAK/STAT signaling pathway, regulated by cytokines like interleukin-6, plays a role in RA pathogenesis, increasing systemic inflammation and extra-articular comorbidities, such as atherosclerosis." (PMID 38256299, 2023).
atherosclerosis (continued). "Myeloid-specific Ezh2 deficiency can reduce macrophage foam cell inflammatory response with reduced production of nitric oxide, IL-6, and IL-12, contributing to reduced atherosclerosis in mice." (PMID 38031118, 2023). "For example, IL-1 is involved in developing atherosclerosis and can promote the production of other inflammation-promoting cytokines, including IL-6." (PMID 37637634, 2023). "IL-6 is known to increase inflammation and the development of vascular diseases, including atherosclerosis." (PMID 38136193, 2023). "Interleukin 6 (IL‐6), a pro‐inflammatory cytokine with a 26 KDa molecular weight, is closely involved in regulating inflammation, atherosclerosis progression, and cardiovascular diseases." (PMID 37102647, 2023). "Going “upstream” in the pathophysiological chain of atherosclerosis-related inflammation, IL-6 plays a central role, along with IL-1, in this process." (PMID 37629496, 2023). "Many inflammatory markers were shown to be related with atherosclerosis and cardiovascular diseases, such as interleukin-6 (IL-6), D-dimer, and high-sensitivity C-reactive protein (hs-CRP)." (PMID 36849967, 2023). "Previous studies have shown that targeting IL-6 signaling pathways is beneficial to patients with atherosclerosis and has emerged as a key factor in managing atherothrombosis." (PMID 38104193, 2023). "In high-fat-diet-fed ApoE−/− mice, empagliflozin was reported to activate AMPK, inhibit atherosclerosis progression, and decreased IL-1β and IL-6 levels." (PMID 37373164, 2023). "Apart from IL-1, IL-6 represents a further crucial pro-inflammatory cytokine contributing to atherosclerosis and plaque destabilization." (PMID 38138958, 2023). "Atherosclerosis is one of the leading causes of AMI, and inflammatory mediators such as IL-6, TNFα, and CRP are potential biomarkers for the diagnosis of AMI in patients with angina." (PMID 36672669, 2023). "These mice exhibited increased expression of several genes of the CXC chemokine gene cluster, including CXCL1, CXCL2, CXCL3, and Pf4, and classic proinflammatory cytokine genes such as IL-1ß and IL-6, which contribute to atherosclerosis." (PMID 38162500, 2023). "Previous studies have shown that IL-6, whose levels are increased in IBD, is linked to endothelial dysfunction, thrombocytosis, early atherosclerosis, and CAD." (PMID 38001946, 2023). "Abnormal immune system response promotes inflammation and inflammatory cytokines (TNFα, IL-6, and IL-1β) that also contribute to the initiation and progression of atherosclerosis and also to the depletion of T cells." (PMID 37627941, 2023). "Several studies demonstrated that patients with atherosclerosis and ischemic stroke exhibited an increase in serum levels of pro-inflammatory cytokines including IL-8 and IL-6 compared to normal individuals." (PMID 36741286, 2023). "Upstream movement of the inflammatory cascade from CRP to IL-6 to IL-1 offers new therapeutic opportunities for atherosclerosis protection." (PMID 36873405, 2023). "Mast cells also contribute to atherosclerosis by secretion of cytokines and chemokines such as IL-6, IL-8, TNF-α, IFN-γ, histamine, and proteases." (PMID 37600028, 2023). "With age, the phenomenon of clonal hematopoiesis of indeterminate potential in the bone marrow increases, the function of thread granules decreases, and IL‐6 level in the vasculature increases, all of which promote the formation of atherosclerosis." (PMID 37137812, 2023). "This was evidenced by a consistent macrophage phenotype characterized by significant upregulation of CXCL1, CXCL2, CXCL3, and IL-6, ultimately contributing to the promotion of accelerated atherosclerosis." (PMID 38162500, 2023). "Emerging research has provided substantial evidence indicating that IL-6 expression exhibits varying degrees of elevation in cardio-cerebrovascular conditions, such as atherosclerosis, myocardial infarction, heart failure, and ischemic stroke." (PMID 37762312, 2023).
atherosclerosis (continued). "The adipose tissue-derived exosomes induce RAW264.7 macrophages to switch to the M1 phenotype, increase the secretion of pro-inflammatory cytokines (TNF-α, IL-6), and exacerbate atherosclerosis in hyperlipidemic ApoE−/− mice." (PMID 36683743, 2023). "Mainly, MSCs derived from individuals with atherosclerosis develop a pro-inflammatory secretome by the production of inflammatory cytokines such as IL6, IL8, and MCP1, reversing their naturally immunosuppressive properties." (PMID 37626416, 2023). "RESCUE is another recent randomized trial which tested the effects of Ziltivekimab, an antibody-mediated IL-6 inhibitor explicitly developed for atherosclerosis." (PMID 37629496, 2023). "Ziltivekimab is an IL-6 inhibitor that has emerged as a promising therapy for reducing the incidence of atherosclerosis-related thrombosis." (PMID 38003290, 2023). "In atherosclerosis, microRNA binding directly to human RNA-binding protein (HuR) regulates the formation of IL-6, TNF-α, IL-1β, and myocardial fibrosis via fibroblast activation and expansion." (PMID 38203612, 2023). "OxLDL, which is a risk factor for atherosclerosis, has also been shown to stimulate PKC, influence NF-kB and AP-1 activity, and stimulate cytokine expression, including IL-6 and IL-8." (PMID 37108469, 2023). "Through acute-phase proteins such as CRP or cytokines such as TNF-α and IL-6, chronic inflammation greatly contributes to atherosclerosis in both the tunica intima and tunica media layers of the arterial wall." (PMID 37893519, 2023). "The altered circulating miRNAs in this study are believed to be involved in biological signaling pathways including IL-6 signaling, atherosclerosis signaling, and acute phase response signaling, implicating vascular inflammation and injury." (PMID 37624035, 2023). "When stimulated with ox-LDL, in other inflammatory states, like atherosclerosis, macrophages responded with an increased expression of TNFα (tumor necrosis factor-alpha) and IL-6 (interleukin 6) genes." (PMID 37251403, 2023). "IL-6 enhanced the formation and rupture of atherosclerotic plaques, hence accelerating the progression of atherosclerosis." (PMID 37104297, 2023). "Production of key pro-inflammatory mediators, such as MCP-1, IL-8 and IL-6, by recruited plaque monocyte-derived macrophages is a key component of the vascular inflammation observed in atherosclerosis and CAD." (PMID 37849759, 2023). "Recently, several components of the immune system have been targeted in an attempt to reduce inflammation leading to atherosclerosis with anti-interleukin-1 (IL-1) and anti-interleukin-6 (IL-6) targeted therapy showing promising results." (PMID 36723716, 2023). "The relationship between IL-6, exercise, and atherosclerosis remains largely untouched and urgently requires further research." (PMID 36834808, 2023). "For example, data from the US Multi-Ethnic Study of Atherosclerosis found that RHR was correlated with serum IL-6, hsCRP, and fibrinogen in middle-aged and older people free of CVD." (PMID 37898962, 2023). "The pro‐inflammatory cytokines, including IL‐1β, Interleukin 6 (IL‐6) and tumour necrosis factor‐alpha (TNF‐α), have been regarded as the risk factors in atherosclerosis." (PMID 37905351, 2023). "Serum concentrations of C-reactive protein (CRP), interleukin-6 (IL-6), and LDL are highly correlated with clinical symptoms of atherosclerosis and an increased risk of death from cardiovascular disease." (PMID 37570897, 2023). "Once monocytes are recruited to the site of inflammation interleukin 6 (IL‐6) is secreted which further perpetuates inflammation with further progression of atherosclerosis." (PMID 37457144, 2023). "CRP and IL-6, as markers of inflammation, have been widely studied and described as factors in the development of atherosclerosis." (PMID 37509461, 2023).